LPO (lactoperoxidase)
Diseases named in the same sentence as LPO in open-access papers (continued):
Sharing a sentence is not in itself a finding about the gene and the disease.
pneumococcal infection (1 paper, 2020). Infections with bacteria of the species streptococcus pneumoniae. "Airway epithelial cells, the primary responders to pneumococcal infection, orchestrate an extracellular antimicrobial system consisting of lactoperoxidase (LPO), thiocyanate anion and hydrogen peroxide (H2O2)." (PMID 32730276, 2020).
prostate carcinoma (1 paper, 2021). A carcinoma that arises from epithelial cells of the prostate gland. "Also, TGF-β increased the expression of ID1 and ID3 in prostate cancer cell lines and so far, only lactoperoxidase was reported to decrease ID1 and ID3 expression on oral squamous oral epithelial cell line." (PMID 33477984, 2021).
respiratory infections (1 paper, 2023). "Lactoperoxidase (LPO) is a mammalian heme peroxidase that is released from the mucosal membrane of the airways and has been shown to reduce respiratory infections." (PMID 36648852, 2023).
thyroid autoimmunity (1 paper, 2024). "Cross-reactivity between thyroid peroxidase (TPO) and lactoperoxidase (LPO) due to their structural similarities can also contribute to thyroid autoimmunity." (PMID 38952602, 2024).
type 1 diabetes mellitus (1 paper, 2020). A chronic condition characterized by minimal or absent production of insulin by the pancreas. "When the hesperetin was tested in streptozotocin (STZ)-induced type 1 diabetes mellitus (T1DM), the findings suggested that the level of LPO, GSH, and antioxidant genes (Nrf2 and HO-1) were significantly upregulated with the administration of hesperetin." (PMID 32664395, 2020).
ulcer (1 paper, 2021). "In ulcer-induced group the anti oxidant enzymes SOD, CAT, GPX, LPO and MPO were decreased when compared with control group." (PMID 34393417, 2021).
cancer (10 papers, 2011 to 2024). A tumor composed of atypical neoplastic, often pleomorphic cells that invade other tissues. "In the present study, the cancer patients had a lower relative abundance of Lactoperoxidase at 6 months post-treatment compared with the healthy controls." (PMID 39640734, 2024). "Analysis of the levelsof lactoperoxidase, malondialdehyde, lactic acid, total glutathione,and ATP suggested that the in vivo inhibition of cancer cell proliferationby 15 went through stimulation of oxidative stress injuryand Fe2+ accumulation." (PMID 36395526, 2022). "In this investigation, we exposed the interaction of LPO with the prepared GO-SA composite to yield the modified GO-SA-LPO complex, which increases the retention of LPO and enhances its application as an anticancer candidate for treating many types of cancer cell lines." (PMID 39438495, 2024). "The R_cancer prognosis features and risk score were calculated as: MOCS1 × 1.100 − PTGS2 × 0.722 + PLEKHA8P1 × 0.409 − ZC3H12C × 0.571 + LPO × 0.575 + METTL11B × 0.294 + RP11-278A23.1 × 0.508 + RP11-452K12.7 × 0.405 − RP11-742B18.1 × 0.360 + RP11-626H12.2 × 0.787." (PMID 36419007, 2022). "Moreover, the anticancer activity of free LPO, the modified GO-SA nanocomposite, and the modified GO-SA-LPO nano-combination against normal human lung fibroblast WI-38 cells and both colon (Caco-2 and HCT-116) cancer cell lines were also investigated." (PMID 39438495, 2024).
tumor (9 papers, 2013 to 2025). "Increasing LPO can reverse tumor resistance and improve the chemotherapeutic effects of multikinase inhibitors." (PMID 38645554, 2024). "The results revealed that expression levels of SLCO4C1, POU4F1, DNASE1L2, WDR72, LPO, and C7 in tumor tissues were significantly higher than those in normal tissues, while the expression differences of SLC4A4, CELF4, and SLC11A1 were not statistically significant." (PMID 37745305, 2023). "The high expression of CELF4, LPO, SLC11A1, and C7 in tumor tissues might be associated with poor prognosis, but they were not statistically significant (p-values of 0.09, 0.094, 0.06, and 0.21, respectively)." (PMID 37745305, 2023). "Cin showed a protective role against TeA induced tumours in the stomach, and thus elevated the activity of SOD, CAT and LPO in prophylaxis groups." (PMID 34593834, 2021).
infection (4 papers, 2017 to 2024). The state of being infected such as from the introduction of a foreign agent such as serum, vaccine, antigenic substance or organism. "LPO was significantly elevated after infection, and post-treatment with Protect in the TAI group reduced LPO levels." (PMID 36234864, 2022). "Additionally, another stress gene, LPO, first described in connection with lipid peroxidation and strongly related to oxidative stress conditions, showed increased expression at the 3rd hour following infection (LPO, Fc.: 5.05×)." (PMID 38787238, 2024).
bacterial infections (3 papers, 2021 to 2024). "LPO catalyzes the oxidation of thiocyanate into hypothiocyanous acid and plays a role in airway defense against bacterial infections." (PMID 38889046, 2024).
respiratory diseases (1 paper, 2024). "LPO dysfunction can impair immune responses and exacerbate inflammatory processes in respiratory diseases." (PMID 39192275, 2024).
LPO also shares sentences with these, for which no sentence is quoted: xerostomia (3 papers); melanoma (2); oral diseases (2); acne (1); Anxiety (1); fungal infections (1); gingivitis (1); Graves disease (1); heart diseases (1); Hepatitis (1); infectious disease (1); lactose intolerance (1); lung carcinoma (1); lymphosarcoma (1); malnutrition (1); metastatic colorectal cancer (1); myocardial infarct (1); Nasal Polyps (1); osteoporosis (1); pressure ulcers (1); renal fibrosis (1); respiratory distress syndrome (1); Salmonella Infections (1); Stroke (1).